BTK (Bruton tyrosine kinase)
Diseases named in the same sentence as BTK in open-access papers (continued):
Sharing a sentence is not in itself a finding about the gene and the disease.
tumor (continued). "Multiple studies have been made to identify sensitive patients who may potentially benefit from BTK inhibitors, based on tumor genetics, clinicopathology features, or both." (PMID 36505470, 2022). "In this context, the expression of BTK in solid tumors derived from non-hematopoietic lineage cells requires more stringent scrutiny in future studies, especially given the frequent presence of BTK-expressing infiltrating immune cells in the TME of primary tumor specimens." (PMID 34778053, 2021). "Notably, the expression levels of KLRG1, BTK, CCR2, SCML4 were all associated with neoplasm disease stage (American Joint Committee on Cancer Code) (P = 0.001; P = 0.022; P = 0.004; P = 0.014, respectively)." (PMID 34187403, 2021). "A dominant kinase activity in the tumour tissue was Bruton tyrosine kinase (BTK)." (PMID 34645618, 2021). "Moreover, the ability of tumor cells to develop resistance to single-agent checkpoint inhibitors has resulted in clinical studies utilizing BTK inhibitors in combination with these agents to improve clinical responses." (PMID 33818636, 2021). "BTK also contributes to tumor cell proliferation and survival in B cell leukemia and lymphoma." (PMID 33818636, 2021). "Furthermore, activation of BTK was detected in MDSCs isolated from tumor-bearing mice, as well as human samples." (PMID 34063667, 2021). "Moreover, Gunderson and colleagues identified PI3Kγ-mediated regulation of Bruton’s tyrosine kinase (BTK) in macrophages as a key regulator of anti-tumor responses in a murine model of PDAC." (PMID 33924237, 2021). "Thus, these two examples demonstrate a striking heterogeneous and inverse expression between SOX2 and BTK proteins in the same tumour." (PMID 34645618, 2021). "Therefore, we set out to define the cell type(s) in which BTK protein is expressed in GBM tumour tissue to better inform an interpretation of this emerging clinical trials data and better stratify patients." (PMID 34645618, 2021). "First and foremost, BTK inhibition directly inhibits MM tumor growth." (PMID 34071917, 2021). "Furthermore, the immunohistochemical analyses indicated the lowest BTK staining in the tumor section from the combination group, followed by Acalabrutinib only group, while BTK staining remained high in both Osimertinib only group and vehicle group." (PMID 34315851, 2021). "Unfortunately, the onset of different side-effects and BTK mutations in the active site (Cys481), gatekeeper (Thr474), and SH2 (Thr316) domains could lead to tumor cell proliferation." (PMID 34885993, 2021). "Therefore, besides promoting tumor cells proliferation, BTK activation also can inhibit apoptosis through NFκB signaling pathway in non-GCB-DLBCL." (PMID 33827598, 2021). "The expression of BTK in different tumor types also implies this point." (PMID 34187403, 2021). "The combined inhibition of BTK (“on-target” effect) and other kinases (“off-target” effect) can have additive or synergistic anti-tumor effects but also induce undesired side effects which might be treatment-limiting." (PMID 34276674, 2021). "In this study, by examining surgical specimens from 80 NSCLC patients and their clinicopathologic parameters, we found significant correlation between high BTK expression and tumor differentiation, p-stage, lymph node metastatic status, maximum tumor size, and poor prognosis of patients." (PMID 34315851, 2021). "In this study, we evaluated the expression of BTK in NSCLC tumor tissues and cell lines, analyzed its clinicopathologic significance in patients with NSCLC, and investigated its functional roles in NSCLC tumorigenesis, with focus on epithelial–mesenchymal transition (EMT) and stemness." (PMID 34315851, 2021). "Therefore, a question emerges on the value of targeting BTK within tumour tissue and/or how to manage patient stratification to maximize the exploitation of BTK as a therapeutic target." (PMID 34645618, 2021).
tumor (continued). "Moreover, targeting BTK in myeloid cells has shown recent progress and holds therapeutic promise for modulating the tumor microenvironment." (PMID 33818636, 2021). "Together, our GBM data suggest that BTK protein may be expressed in SOX2-positive tumour cells, CD163-positive macrophages, and a third population of cells which needs further characterisation." (PMID 34645618, 2021). "The BTK/ITK inhibitor ibrutinib reprogrammes the tumour-induced immunosuppressive population of myeloid lineage (MDSCs) into mature DCs by blocking BTK, increases the proportion of mature DCs in the tumour and lymphoid organs, and promotes antitumour T cell activity." (PMID 32025027, 2020). "The Th2-driven responses promoting PDAC also depend on B cells and FcRγ+ tumor-associated macrophages (TAMs) expressing Bruton tyrosine kinase (BTK) independent of PI3Kγ." (PMID 33022971, 2020). "In fact, various cell types in the tumor environment express BTK, and these cells might be affected/suppressed by ibrutinib treatment." (PMID 32455989, 2020). "BTK expression in tumor tissue was decreased in a dose-dependent manner." (PMID 32532074, 2020). "In addition to their direct anti-tumor effect, new targeted drugs (i.e. BTK inhibitors, PI3K inhibitors, and the Bcl-2 inhibitor venetoclax) have demonstrated the ability to modulate non-neoplastic immune cell populations." (PMID 33312177, 2020). "Oppositely, BTK-deficient macrophages show defects in fungal phagocytosis and TLR-mediated phagocytosis of tumor cells seems to be impaired by ibrutinib treatment of macrophages, implying a relevant role of BTK in the phagocytic activity of innate immune cells." (PMID 32983178, 2020). "This defines a novel role of BTK in tumour suppression (Rada, Barlev, & Macip, 2018b)." (PMID 31736210, 2020). "The outcomes of this study show that BTK inhibition in combination with Epo may be beneficial and desirable, as this therapeutic scheme effectively inhibit tumour growth via enhancement of apoptosis." (PMID 32912025, 2020). "BTK expression in primary tumours and metastases to lymph nodes." (PMID 32912025, 2020). "Targeting Bruton’s tyrosine kinase (BTK) expressed in MDSCs in tumor-bearing mice by Ibrutinib, an irreversible inhibitor of BTK and IL2-inducible T-cell kinase which widely used for the treatment of B-cell malignancies in clinical, reduces the frequency of MDSCs in both the spleen and tumor." (PMID 32508809, 2020). "Interestingly, both BTK-positive and BTK-negative primary tumours were found to produce BTK-positive as well as BTK-negative metastases." (PMID 32912025, 2020). "This expression was dependent on activation of either NF-κB, JAK1/JAK2 or BTK pathways since these pathways were activated in tumor B-cells and ex vivo treatment with the inhibitory molecules PHA-408, ruxolitinib and ibrutinib led to decrease of its expression." (PMID 31382969, 2019). "Additionally, splenic-derived B cells isolated from tumor-bearing mice polarized macrophages to a Th2 phenotype and a Bruton's tyrosine kinase (BTK) inhibitor, which targets B cells and myeloid cells, demonstrated reduced tumor growth in the orthotopic model." (PMID 30972056, 2019). "Here, for the first time, we investigate whether the combination of PKCβ inhibitor enzastaurin and BTK inhibitor ibrutinib has synergistic anti-tumor effects in DLBCL." (PMID 30777096, 2019). "As previously reported, BTK plays a crucial role in the immune-suppressive state of the tumor." (PMID 31238520, 2019). "Based on this mechanism, we investigated whether the combination of PKCβ inhibitor enzastaurin and BTK inhibitor ibrutinib had synergistic anti-tumor effects in DLBCL." (PMID 30777096, 2019).
tumor (continued). "Moreover, BTK functions in several myeloid cell populations representing important components of the tumor microenvironment." (PMID 29455639, 2018). "Moreover, BTK inhibition shows promise as a therapy that influences crucial immune cells in the tumor microenvironment." (PMID 29455639, 2018). "Indeed, residual tumor cells isolated from the blood of CLL patients taking BTK inhibitors such as ibrutinib or acalabrutinib have been shown to be highly sensitive to venetoclax." (PMID 30406027, 2018). "Importantly, BTK has received large interest since small-molecule inhibitors of this kinase have shown excellent anti-tumor activity in clinical studies." (PMID 29455639, 2018). "MDSCs commonly express BTK and are present in the tumor microenvironment of many different cancers." (PMID 29561760, 2018). "These novel roles of BTK suggest that it could contribute to the activation of other tumour suppressor pathways as well." (PMID 30245853, 2018). "Finally, we discuss the effects of BTK inhibitors on tumor growth in solid malignancies in the context of the function of myeloid cells in the tumor environment." (PMID 29455639, 2018). "It will be important to carefully consider the different activities of BTK when using inhibitors in the clinic, since blocking tumour suppressor pathways could be an undesired side effect." (PMID 30337526, 2018). "The BTK subcellular localization in tumor cells is a key process for the activation of the pathway and BTK mutations affecting this functional domain may also be related with BCR signaling activation." (PMID 29340061, 2017). "Recently, BTK has been shown to highly express in several solid tumors and may contribute to tumor development." (PMID 28946903, 2017). "Moreover, the present report also stresses that the tumour suppressor functions of BTK are important and can be physiologically relevant in the context of preventing the growth of solid tumours." (PMID 29290977, 2017). "B cell depletion in the clinic using anti-CD20 antibodies and/or inhibitors of BTK and/or other signaling pathways, may be a useful strategy for augmenting the anti-tumor immune response." (PMID 27437104, 2016). "In summary, the anti-tumor progression efficacy combined with the already clinically validated safety profile during clinical testing as a BTK kinase inhibitor makes ibrutinib a potentially useful drug candidate for first line treatment of EGFR primary mutation- driven NSCLC." (PMID 26375053, 2015). "Moreover, the activation of Bruton’s tyrosine kinase (BTK) in TIL-Bs has been found to drive the reprogramming of tumor-infiltrating macrophages to the M2 phenotype, impairing CD8+ T-cell-mediated antitumor responses, and contributing to the progression of PDAC." (PMID 39682280, 2024). "Thus, a different regulation of BTK-p65 activity in tumor cells is expected." (PMID 36612306, 2023). "Therefore, it is difficult to distinguish whether the signal derived from BTK in tumor or from BTK in immune cells." (PMID 36612306, 2023). "Moreover, the evidence that BTK is also expressed on many hematopoietic cells suggests that the huge success of the BTK inhibitors in CLL also appears to be related to its pleiotropic activity on cells of the tumor microenvironment." (PMID 37894425, 2023). "However, BTK can also perform oncogenic functions in other tumor cells." (PMID 37638060, 2023). "It has been studied that the expression of BTK is correlated with clinic characteristics (tumor staging and metastasis) negatively and related to the survival of LUAD patients positively, and BTK may be responsible for maintaining the immunodominant state of the tumor microenvironment." (PMID 35437508, 2022). "When combined with anti-CD20 monoclonal antibodies or BTK inhibitors, anti-tumor efficacy could be." (PMID 35303910, 2022).
tumor (continued). "In the last decade data piled up indicating that BTK – for twenty years considered as a “private matter” of bone marrow-derived cells – it is expressed and plays important and different roles also outside of the hematopoietic compartment and, most notably, in tumor cells." (PMID 35992808, 2022). "Taken together, these data suggest that the biology relevant to ibrutinib activity in FL may extend beyond the BTK‐NF‐κB pathway, to epigenetic changes in the expression of key tumor‐related genes, gene and protein regulation, DNA repair, cell cycle progression, and other cellular processes." (PMID 34791836, 2022). "Immunofluorescence assays of tissue sections showed that BTK was mainly located in macrophages at the junction of cancer nest and stroma, and negatively correlated with the abundance of NK cells, suggesting that BTK promotes tumor progression by promoting local immunosuppression." (PMID 34805160, 2021). "Furthermore, BTK-deficient or ibrutinib/acalabrutinib-treated monocytes and macrophages show defects in TLR-mediated phagocytosis of tumor cells as well as TLR9-, TREM-1 and Dectin-1-dependent production of inflammatory cytokines and phagocytosis upon fungal infection." (PMID 34485307, 2021). "BTK activity may impact how epithelial tumor cells interact with bone niches." (PMID 34307353, 2021). "Besides the kinases it activates, the BCR has also been shown to play a role in controlling integrin α4β1 (VLA-4)-mediated adhesion of B cells to VCAM and fibronectin, alluding to the role BTK can play in the metastasis of B cell malignancies and their tumor-stroma interactions." (PMID 34071917, 2021). "Thus, the biological regulation of BTK appears quite distinct between the tumour grades which might have implications for the use of BTK kinase inhibitors as potential therapeutics." (PMID 34645618, 2021). "As the spleens and tumours of ibrutinib-treated mice contained higher proportions of mature DCs, we explored whether or not ibrutinib can promote the development of DCs from MDSCs, which are known to express BTK and hence could be targeted by ibrutinib." (PMID 32025027, 2020). "Therefore, we aimed to investigate whether the combination of PKCβ inhibitor enzastaurin and BTK inhibitor ibrutinib has synergistic anti-tumor effects in DLBCL." (PMID 30777096, 2019). "However, in certain contexts, BTK can also have tumour suppressor functions." (PMID 30245853, 2018). "Recent studies have shown that signaling pathways regulated by TLRs, CSF1R, PI3Kγ, and BTK control macrophage polarization; here, we showed that CD11b promotes miRNA Let7a expression and inhibits Myc expression to control of macrophage polarization and tumor immune responses (Schematic)." (PMID 30568188, 2018). "Finally, we showed that CGI-1746, a novel and potent BTK inhibitor, could induce MM cellular senescence and inhibit MM cells colony formation in vitro and reduce xenografted tumor derived from MM cell lines in vivo." (PMID 28915637, 2017). "Novel BTK inhibitors may be helpful in reducing MM tumor burden partly and indirectly through reduction of osteolytic activity in bone microenvironment, and directly when combined with clinical cell proliferation inhibitors such as certain alkylating agents and proteasome inhibitors." (PMID 25083818, 2014). "The TLT subtype, clustered by 45 genes involved in the cell cycle and DNA damage and repair, had higher expression of B-cell markers, BTK, BCR signaling genes, and MKI67, suggesting proliferative tumor cells as the cell resource." (PMID 39866884, 2025). "Through inhibiting Bruton Tyrosine Kinase (BTK) signaling and blocking Ca2+ influx, Breg-derived eAdo can suppress the B-eff function in the tumor." (PMID 41583489, 2025).
tumor (continued). "The inhibitory effect of ibrutinib on Bruton's tyrosine kinase (BTK) reduces the ADO production by downregulating CD39, significantly increasing B cell infiltration and impede tumor progression in HNSCC." (PMID 39744696, 2025). "In our study, functional enrichment analysis of 2160 proteins commonly expressed in 13qCLL/MBL tumor cells identified critical phosphoproteins involved in BCR signaling, immune response regulation, and cell cycle regulation, such as BTK, PRKCB, STAT1, and SYK." (PMID 40129242, 2025). "Despite these noteworthy findings, more efforts should be conducted to investigate the effects of MGD-C9 as a single agent or combined with inhibitors of BTK and IDH1, respectively, in xenograft tumor models." (PMID 41050081, 2025). "Our findings therefore support a role of BTK inhibition in reversing CAR T‐cell exhaustion, particularly in stromal‐protected tumor regions." (PMID 41368078, 2025). "Specific alterations in BTK’s regulatory elements, alongside perturbed BCR signaling, collectively contribute to sustained pathway activation and fuel tumor growth." (PMID 39062757, 2024). "Strikingly, significant decreases in lactate and alanine were detected in vivo as early as two and seven days after the initiation of BTK inhibitor therapy and directly corresponded with the suppression of MCL tumor growth." (PMID 38965536, 2024). "When combined with CAR-T therapy, BTK inhibitors enhance the efficacy of CAR-T therapy against malignant tumors by modulating T cell function and remodeling the tumor immune microenvironment." (PMID 39026380, 2024). "Treatment with BTK (MCL) and EGFR (NSCLC) inhibitors increased target ligand, conditionally driving CER-1236 function to augment anti-tumor responses." (PMID 37194236, 2023). "This may be one of the reasons for the limited anti-tumor effect of tirabrutinib in U-2932, and this finding was consistent with that of a previous study, which demonstrated that the contribution of AKT signaling to survival in U-2932 causes the low sensitivity to BTK inhibitors." (PMID 36897912, 2023). "Having observed BTK-p80 as well as BTK-p65 expression in HNSCC cell lines and tumor specimens we further investigated the molecular and cellular consequences of this finding for HNSCC tumorigenesis." (PMID 36612306, 2023). "Since we revealed that BTK inhibition reduces HNSCC autonomous cell growth in vitro, we next aimed to examine its effect in tumor progression in vivo." (PMID 36612306, 2023). "When we suppressed the signaling transfer through this cascade by inhibitors of SYK, BTK and PI3 kinases, i.e. by P505-15, ibrutinib and wortmannin, respectively, in Nawalma tumor cells, we observed the relocation of nuclear NFATc1 into cytosol." (PMID 37546418, 2023). "Overall, treatment with the BTK inhibitor AVL-292 induced significant morphological alterations, including changes in the size, number, and morphology of HNSCC tumor cells cultured under 3D conditions." (PMID 37685940, 2023). "Pharmacologic inhibition of the BTK-IDO axis and deletion of BTK/IDO genes led to the robust differentiation of inflammatory DCs and promoted anti-tumor T cell responses both in vitro and in vivo." (PMID 37277776, 2023). "In summary, the addition of the IRAK4 inhibitor emavusertib was beneficial to the anti-tumor activity of PI3K and BTK inhibitors and it can also overcome the acquired resistance in MZL models." (PMID 36675328, 2023). "Overexpression of BTK can significantly inhibit the proliferation, migration, and invasion of NSCLC cells and can block the G0/G1 tumor cell cycle, indicating that overexpression of BTK can inhibit the growth, migration, and invasion of NSCLC cells." (PMID 37638060, 2023). "Taken together, these data show that BTK inhibition by AVL-292 negatively impacts HNSCC proliferation by inducing cell cycle arrest, apoptosis and autophagy in tumor cells." (PMID 36612306, 2023).